NEB (nebulin)
Diseases named in the same sentence as NEB in open-access papers (continued):
Sharing a sentence is not in itself a finding about the gene and the disease.
nemaline myopathy (continued). "For OM to be useful for increasing skeletal muscle force in nebulin-based nemaline myopathy patients, undesirable effects in the heart have to be avoided." (PMID 31721788, 2019). "The commonest forms of nemaline myopathy are caused by mutations in the genes encoding skeletal muscle α-actin (ACTA1) and nebulin (NEB)." (PMID 31228046, 2019). "Efforts are concentrating on the most commonly mutated genes causing nemaline myopathy, ACTA1 and NEB, and descriptions have been published of a variety of knock-in and knock-out mouse models of causative mutations in these genes." (PMID 31228046, 2019). "Loss of KLHL41 or inhibition of its poly-ubiquitination leads to NEB aggregation, sarcomere disarray and nemaline myopathy." (PMID 28826497, 2017). "NEB, which plays an important role in regulating thin filament length, is the most frequently affected gene in nemaline myopathy with patients exhibiting muscle weakness and reduced force generation." (PMID 25931053, 2015). "Mutations in ten different genes cause nemaline myopathy: skeletal muscle α-actin (ACTA1), nebulin (NEB), α-tropomyosin, β-tropomyosin, troponin T1, cofilin 2 (CFL2), KBTBD13, KLHL40, KLHL41 and leiomodin 3 (LMOD3)." (PMID 25931053, 2015). "Structural variants (SVs) of the nebulin gene (NEB), including intragenic duplications, deletions, and copy number variation of the triplicate region, are an established cause of recessively inherited nemaline myopathies and related neuromuscular disorders." (PMID 40517164, 2025). "In seven patients with nemaline myopathy, the authors identified several causal variants in the ACTA1 gene (in one patient), the LMOD3 gene (in two patients), the PLOD1 gene (in one patient), and the NEB gene (in four patients)." (PMID 37989827, 2024). "Our finding that force is reduced in some patients despite a relatively normal level of nebulin bears resemblance to the findings in a mouse model of typical nemaline myopathy wherein a decrease in specific force was noted despite the presence of normal nebulin levels." (PMID 38634969, 2024). "Except NEB gene mutation, ACTA1 gene mutation is the most common one that cause nemaline myopathy." (PMID 33742414, 2022). "Typical, less severe, nemaline myopathy (NM), is caused by mutations in the nebulin gene (NEB) rather than the absence of nebulin." (PMID 35328477, 2022). "Moreover, recent studies have only expanded upon the complexities of nebulin function and its role in nemaline myopathy." (PMID 31992366, 2020). "Thus, tirasemtiv significantly improves muscle function in a mouse model of nebulin-based nemaline myopathy." (PMID 31658633, 2019). "Similarly, a reduction in Nebulin in zebrafish recapitulates many of the clinical and pathological aspects of nemaline myopathy observed in patients." (PMID 29848386, 2018). "Recent studies on mouse models deficient in nebulin indicate that the large filamentous protein nebulin plays an important role in each of these force determinants and, importantly, that when nebulin levels are reduced in nemaline myopathy (NM) patients, severe muscle weakness ensues." (PMID 23437068, 2013). "Nebulin was suggested to be involved in thin filament length regulation, because reduced nebulin protein levels result in abnormal thin filament lengths in NEB-related nemaline myopathy patients as well as in nebulin deficient mouse models, zebrafish and chick skeletal myocytes." (PMID 31982973, 2020). "This may indicate that, while the expression of the Z-disk fragment in nebulin-deficient muscle has slowed the progression of structural changes in nemaline myopathy, it has not been sufficient to alter some regulatory proteins." (PMID 31992366, 2020). "Nebulin (NEB) plays an important role in regulating thin filament length and is the most frequently affected gene in nemaline myopathy, accounting for approximately 50% of all cases." (PMID 29848386, 2018).
nemaline myopathy (continued). "Nebulin is a sarcomeric protein that when absent (NEB KO mouse) or present at low levels (nemaline myopathy (NM) patients with NEB mutations) causes muscle weakness." (PMID 23437068, 2013). "Pathogenic homozygous or compound heterozygous variants in Nebulin gene (NEB; MIM 161650) are associated with nemaline myopathy (NEM2; MIM 256030), a non-dystrophic congenital myopathy." (PMID 41465143, 2025). "In addition to NM, mutations in NEB cause distal nebulin myopathy with no or almost no nemaline bodies, a condition so far described only in Finland, distal myopathy with nemaline bodies (distal nemaline myopathy), and rare cases of core-rod myopathy." (PMID 25110572, 2014). "As nebulin is a massive, multi-functional protein, treatment of nemaline myopathy might not be attainable to a sufficient degree with only a Z-disk fragment and additional studies will be needed first." (PMID 31992366, 2020). "A prime example is nemaline myopathy (NM), the most common non-dystrophic congenital skeletal muscle myopathy that is caused by mutations in six genes that all encode thin filament proteins (TMP2, TMP3, NEB, ACTA1, TNNT1, CFL2)." (PMID 23437068, 2013).
congenital myopathy (17 papers, 2011 to 2025). "Biallelic pathogenic variants in the gene encoding nebulin (NEB) are a known cause of congenital myopathy." (PMID 38585796, 2024). "Persons with distal forms of congenital myopathy had either homozygous missense, dominant, or de novo mosaic large deletions in NEB, and those with unspecified forms had dominant TPM2 variants." (PMID 38037113, 2023). "Of note, functional studies are needed when mutations are detected in the RYR1 and NEB genes which are associated with congenital myopathies, as variants of uncertain significance are common in these genes due to their large size." (PMID 34193198, 2021). "This phenomenon has already been observed for various congenital myopathy-related mutations altering thin filament proteins such as tropomyosin and nebulin." (PMID 23029319, 2012). "Here we have described two siblings with compound heterozygote mutations in intron 13 and exon 81 of NEB, resulting in severe congenital myopathy with profound muscle weakness, arthrogryposis and neonatal death." (PMID 21798101, 2011). "The same recessive NEB variant may in one patient be associated with NM, but in another patient, in combination with another recessive variant, cause another, related congenital myopathy." (PMID 40517164, 2025). "Mutations in the NEB gene lead to human congenital myopathies." (PMID 38036415, 2024). "In the congenital myopathy subgroup, 12 of 22 patients (54.5%) had disease-causing variants in RYR1 (n = 4), MYH7 (n = 3), TTN (n = 2), FHL1 (n = 1), NEB (n = 1), and SELENON (n = 1)." (PMID 40494860, 2025). "CNVs of the NEB TRI region are seen in up to 14% of congenital myopathy index patient samples (either heterozygous or homozygous), and approximately half of these are pathogenic." (PMID 40517164, 2025). "With this case report, we want to sensitize clinicians to the common congenital myopathy and its genetic basis of compound heterozygosity in the NEB gene." (PMID 39099920, 2024). "Pathogenic variants in NEB were first described in patients with congenital autosomal recessive (AR) NM type 2 (NEM2, MIM ID #256030), but have since been found to cause other related congenital myopathies as well." (PMID 40517164, 2025). "This is of particular interest for the diagnosis of congenital myopathies, which involve very large genes like RYR1 and NEB as well as genetic and phenotypic heterogeneity." (PMID 23826317, 2013).
distal myopathy (6 papers, 2008 to 2025). Distal myopathy refers to a group of muscle diseases which share the clinical pattern of predominant weakness and atrophy beginning in the feet and/or hands. "More recently, both dominantly inherited distal myopathy and a recessive congenital asymmetric distal myopathy with hemifacial weakness have been linked to large deletions in NEB, further expanding its clinical spectrum." (PMID 40091977, 2025). "For the first time, we establish a clear and statistically significant association between large NEB deletions and a form of distal myopathy." (PMID 40517164, 2025). "These authors described four Finnish families with two different homozygous NEB missense variants and mild distal myopathy." (PMID 34440373, 2021). "Recently, homozygous missense mutations in the nebulin gene (NEB) have been reported to cause a novel distal myopathy, “Distal nebulin myopathy”." (PMID 19325803, 2008).
autosomal recessive Nemaline myopathy 2 (4 papers, 2015 to 2023). "Mutations in the NEB gene are associated with autosomal recessive Nemaline myopathy 2 (OMIM 2560), a congenital form of which may present with US findings during pregnancy, similar to those reported in this fetus." (PMID 27168972, 2016). "The first disorder was arthrogryposis multiplex congenita-6 (AMC6)/Nemaline myopathy-2 (NEM2), which is caused by homozygous or compound heterozygous mutation in the NEB gene on chromosome 2q23." (PMID 37260775, 2023).
centronuclear myopathy (4 papers, 2016 to 2022). Centronuclear myopathy (CNM) is an inherited neuromuscular disorder characterized by clinical features of a congenital myopathy and centrally placed nuclei on muscle biopsy. "It has been reported that severe neonatal bulbar and respiratory muscle involvement occurs particularly in severe NM (most likely ACTA1-, NEB- or KLHL40-related) and MTM1-related myotubular myopathy." (PMID 35081925, 2022).
arthrogryposis multiplex congenita (3 papers, 2022 to 2025). Arthrogryposis multiplex congenita (AMC) is a group of disorders characterized by congenital limb contractures. "Carrier couples (RPL33) were identified with the variants in the NEB gene, which is responsible for AR Arthrogryposis multiplex congenita-6 (AMC6)." (PMID 37260775, 2023).
autosomal recessive nemaline myopathy (3 papers, 2020 to 2023). "Mutations in NEB are the most common cause of autosomal-recessive nemaline myopathy, characterized by Z-disk and thin filament proteins aggregated into nemaline bodies, Z-disk disorganization and consequently, early-onset muscle weakness that mainly affect proximal muscles." (PMID 37576554, 2023).
breast carcinoma (3 papers, 2018 to 2023). "Likewise, HR−HER2-positive breast cancer showed more differentially mutated genes (ERBB2, PRKDC, PTEN and NEB) than HR−HER2-zero breast cancer (only SLX4) compared to HR−HER2-low breast cancer (3 vs 1)." (PMID 37264417, 2023). "The functional roles of NEB in breast cancer have been poorly studied." (PMID 38049758, 2023).
cardiomyopathies (2 papers, 2014 to 2015). "Thus far no nebulin mutations have been reported to be associated with any cardiomyopathies in humans." (PMID 26798563, 2014).
congenital nemaline myopathy (2 papers, 2017 to 2024). A rare genetic muscle disorder defined by muscle weakness and the presence of fine, thread-like or rod-like structures called “nemaline bodies”, when muscle biopsies are viewed under the microscope. "Mutations in these proteins are linked to significant muscular disorders, with nebulin mutations associated with congenital nemaline myopathy." (PMID 38559672, 2024).
distal nebulin myopathy (2 papers, 2014 to 2025). "Homozygous missense mutations in NEB have been found to cause distal nebulin myopathy, and NEB compound heterozygous mutations may result in core-rod myopathy." (PMID 25110572, 2014).
muscular dystrophy (2 papers, 2018 to 2024). Muscular dystrophy (MD) refers to a group of more than 30 genetic diseases characterized by progressive weakness and degeneration of the skeletal muscles that control movement. "A loss or a disruption of sarcomeres and their passive elastic proteins, such as titin, α-actinin, and nebulin, or myofibrillar remodelling in hampered regeneration cycles as in muscular dystrophy, could provide an explanation." (PMID 38672689, 2024). "Many patients with significant respiratory impairment remained ambulant, a feature also shared with early onset SEPN1‐, NEB‐, TPM3‐ ACTA1‐myopathy and COL6‐muscular dystrophy." (PMID 29691892, 2018).
osteosarcoma (2 papers, 2017 to 2023). A usually aggressive malignant bone-forming mesenchymal neoplasm, predominantly affecting adolescents and young adults.
ovarian carcinoma (2 papers, 2008 to 2022). A malignant neoplasm originating from the surface ovarian epithelium. "In taxol-resistant ovarian cancer cells, NEB along with DCDC2, ANKRD18B, ALDH1A1, and ITGBL1 were overexpressed suggesting the involvement of these AR-related genes in taxol resistance." (PMID 35975176, 2022). "It was found to be overexpressed in human breast and ovarian cancer and became the first member of a newly defined LIM-protein subfamily of the nebulin group characterized by the combined presence of LIM and SH3 domains." (PMID 18419822, 2008).
sarcoma (2 papers, 2019 to 2025). A usually aggressive malignant neoplasm of the soft tissue or bone. "Survival analysis of the top ten hub DEGs indicate that overexpression of AC104831.1, CKM, and NEB was significantly associated with poor OS in patients with sarcoma." (PMID 31598169, 2019).
Atrophy (1 paper, 2022). Any weakening or degeneration, especially through lack of use. "In contrast to titin, shortening of nebulin has been associated with the development of muscle atrophy." (PMID 35642060, 2022). "This spaceflight-induced shortening of nebulin may contribute to the development of atrophy in both the gastrocnemius and quadriceps." (PMID 35642060, 2022).
bladder cancer (1 paper, 2025). "This included strong upregulation of cancer‐testis antigens (MAGEA3, MAGEA6, MAGEA10) and neuroendocrine‐associated genes such as NEB and NELL2, features linked to higher tumour grade, invasion and lineage plasticity in bladder cancer." (PMID 41425537, 2025). "LC2 also exhibited elevated expression of NEB, a gene more commonly linked to neuroendocrine and small cell bladder cancer, as well as NELL2, which has been implicated in promoting cell viability and proliferation in bladder cancer cells." (PMID 41425537, 2025).
breast tumors (1 paper, 2023).
colorectal cancer (1 paper, 2022). A primary or metastatic malignant neoplasm that affects the colon or rectum. "In addition to these commonly mutated genes, genomic mutations in SYNE1, TTN, NEB, and CCDC168 were found to be associated with a poor prognosis of colorectal cancer in this study." (PMID 35975176, 2022).
COVID-19 (1 paper, 2023). A disease caused by infection with severe acute respiratory syndrome coronavirus 2. "Patients with COVID-19 have higher levels of NEB expression in their cardiomyocytes." (PMID 37109540, 2023).
esophageal carcinoma (1 paper, 2023). A primary or metastatic malignant neoplasm involving the esophagus. "As for NEB, it was significantly downregulated in BRCA, HNSC, KICH, KIRP, and THCA; up-regulated in BLCA, CHOL, COAD, esophageal carcinoma (ESCA), liver hepatocellular carcinoma (LIHC), LUAD, LUSC, rectum adenocarcinoma (READ), stomach adenocarcinoma (STAD), and UCEC (P < 0.05; P < 0.01; P < 0.001)." (PMID 37340028, 2023).
heart failure (1 paper, 2022). Inability of the heart to pump blood at an adequate rate to meet tissue metabolic requirements. "NEB is an important component of the thin filament and has been described in the context of heart failure and DCM before." (PMID 35980883, 2022).
hereditary cancer (1 paper, 2021). Malignant neoplasms occurring in families at a rate greater than that expected by chance and caused by germline mutations in a specific gene. "Other segdup regions, including NEB (exons 83–103), PMS2 (exons 12–15), PRSS1, and SDHA, accounted for 358 additional findings within the hereditary cancer, neurology, and pediatric indications." (PMID 34007000, 2021).
malaria (1 paper, 2016). Malaria is a serious and sometimes fatal disease caused by a parasite that commonly infects a certain type of mosquito which feeds on humans. "Quite a few differentially abundant proteins such as Haptoglobin (HP), Superoxide dismutase (SOD), Ceruloplasmin (CP), Titin (TTN), Nebulin (NEB), and Vitronectin (VTN) were found to be highly relevant in context of pathophysiology of severe malaria." (PMID 27090372, 2016).
myeloid neoplasm (1 paper, 2022). Proliferation of myeloid cells originating from a primitive stem cell. "For example, alterations in TET2 gene, one of the more commonly mutated genes in myeloid neoplasms, specifically co-occurred with NEB gene variations in control MPN patients, with the odds ratio for the co-occurrence being 11.6 times higher than that seen in MPN patients with SCs (p = 0.0138)." (PMID 35884495, 2022).
neuroblastoma (1 paper, 2013). Neuroblastoma (NB) is the most common solid, extracranial childhood tumor. "We only identified 2 mutated genes (ATRX and NEB) in this neuroblastoma patient that have been reported in the previous studies." (PMID 24147068, 2013). "Out of the 44 mutant genes, only 1 gene (NEB) was reported to be mutated in other neuroblastoma in a published whole genome sequencing study confirming a low frequency of recurrent mutations in this cancer." (PMID 24147068, 2013).
respiratory failure (1 paper, 2024). The significant impairment of gas exchange within the lungs resulting in hypoxia, hypercarbia, or both, to the extent that organ tissue perfusion is severely compromised. "Abnormal expression of nebulin can result in hypotonia, muscle weakness, and, in some cases, respiratory failure, leading to death." (PMID 39474605, 2024).
SARS-CoV infection (1 paper, 2020). "The reduction in the production level of taurine and induction of inflammatory responses was experienced by downregulation of nebulin (NEB) gene in SARS-CoV infection." (PMID 32754004, 2020).
Sepsis (1 paper, 2024). Sepsis is defined as life-threatening organ dysfunction caused by a dysregulated host response to infection. "Decreased in the MIS-C cohort, NEB is a critical skeletal muscle protein and has been suggested to be a sepsis biomarker." (PMID 38632526, 2024).
T-cell lymphomas (1 paper, 2025). "NEB and PCLO variants were infrequent in T-cell lymphomas, including T-LGLL." (PMID 40202536, 2025).